CXCL13 (C-X-C motif chemokine ligand 13)
Diseases named in the same sentence as CXCL13 in open-access papers (continued):
Sharing a sentence is not in itself a finding about the gene and the disease.
lung adenocarcinoma (14 papers, 2016 to 2025). A carcinoma that arises from the lung and is characterized by the presence of malignant glandular epithelial cells. "The elevated level of CXCL13 in the serum serves as a risk factor for the progression of the early stages of lung adenocarcinoma." (PMID 34947813, 2021). "CXCL13 was also identified as a predictive factor for risk of early stage lung adenocarcinoma." (PMID 31354634, 2019). "We investigated the predictive value of CXCL13 to immune checkpoint inhibitors (ICI) in lung adenocarcinoma." (PMID 36453453, 2023). "CXCL13 expression in lung adenocarcinoma showed predictive value to immune checkpoint inhibitor (ICI) treatment." (PMID 36453453, 2023). "The corresponding chemokines (CCL20 and CXCL13) are high-expressed in lung adenocarcinoma and squamous cell carcinoma." (PMID 33777013, 2021). "By analyzing The Cancer Genome Atlas (TCGA) data using log2 (tags per million + 1) for log scale, we found that CXCL13 expression was significantly higher in lung adenocarcinoma (LUAD) and lung squamous cell carcinoma (LUSC) than that in normal lung tissues." (PMID 34553036, 2021). "Both normal lung epithelial (16HBE) and lung adenocarcinoma (A549) cells show upregulated CXCL13 in a dose- and time-dependent manner when the cells are treated with BaP." (PMID 34947813, 2021). "After Bonferroni correction, only CXCL13 and CCL22 were found to be independently related to the risk of early-stage lung adenocarcinoma." (PMID 32714866, 2020). "We observed that CXCL13 upregulation is correlated to better ICI response in lung adenocarcinoma." (PMID 36453453, 2023). "We found CD1A|CXCL13, CD1A|S100A7L2, IFNA7|CMTM2, IFNA7|CSF3, CAMP|TFR2, this 5‐IRGPs were strongly associated with the prognosis of patients, all of which were protective factors for the prognosis of lung adenocarcinoma." (PMID 35246970, 2022). "CXCL13 was initially identified as part of an invasive network module in lung adenocarcinomas." (PMID 31354634, 2019). "In conclusion, we propose further clinical investigations of CXCL13 as a predictive biomarker of ICI treatment in lung adenocarcinoma, which might reflect not only the functional status of cytotoxic T cells but also the tumor microenvironment represented by TLS." (PMID 36453453, 2023). "We used TCGA and GTEx database to analyze the relationship between the expression levels of CXCL13 and CCL20 and the overall survival rate in patients with lung adenocarcinoma (LUAD)." (PMID 40764989, 2025). "To validate these findings, we analyzed the transcriptional and protein expression levels of HER2, CXCL13, and CCL20 in six pairs of clinical lung adenocarcinoma tissue samples." (PMID 40764989, 2025). "Our analysis of 483 LUAD samples and 347 normal tissue samples from the TCGA and GTEx databases revealed that the expression levels of CXCL13 and CCL20 in lung adenocarcinoma tissues were significantly higher compared to normal lung tissues." (PMID 40764989, 2025).
chronic lymphocytic leukemia (12 papers, 2008 to 2022). "Burkle and colleagues demonstrated that incubation of human CXCL13 with chronic lymphocytic leukemia (CLL) cells expressing high levels of functional CXCR5 receptor led to time- and dose-dependent receptor endocytosis." (PMID 25879435, 2015). "Elevated serum CXCL13 levels have recently been reported in other cancers, including B-cell chronic lymphocytic leukemia." (PMID 21490903, 2010). "CXCL13 and CCL19 together can inhibit the TNFα-mediated apoptosis of the CD23+ CD5+ B cell lineage, which is the commonest malignant cell type in acute and chronic lymphocytic leukemia." (PMID 30819249, 2019). "This idea is supported by the findings of others who observed that, in the case of chronic lymphatic leukaemia, CXCR5 and its ligand were overexpressed in malignant B cells but that CXCR5 was downregulated after stimulation with soluble CXCL13." (PMID 18781150, 2008). "Moreover, CXCL13/CXCR5 has been demonstrated to induce significant resistance to TNF-α-mediated apoptosis in B cell lineage acute and chronic lymphocytic leukemia (B-ALL and B-CLL)." (PMID 34947813, 2021).
diabetes (12 papers, 2015 to 2025). "The group with CXCL13-positive stromal cells had significantly lower HbA1c levels and significantly shorter duration of diabetes compared with CXCL12-negative stromal cells." (PMID 40548381, 2025). "Recent work further identified that CXCL13/CXCR5 contributes to diabetes-induced mechanical hypersensitivities by activating pERK, pSTAT3, and pAKT pathways and promoting TNF-α and IL-6 production in SCDH." (PMID 33602238, 2021). "Blocking CXCL13 in the NOD-mouse model for diabetes disrupted the organization of TLO in the pancreas of the mice, however, without affecting disease severity." (PMID 27656182, 2016). "Additionally, CXCL13, CA6, SDC1, and PTN demonstrated mediating effects in the association between Health Behaviors and outcomes such as diabetes, renal disease, and death." (PMID 41290610, 2025). "Similarly, a recent study showed that CXCL13 activates ERK in the spinal cord through CXCR5 in a mouse model of diabetes-induced tactile allodynia." (PMID 33161894, 2020). "CXCL13, CA6, SDC1, and PTN, on the other hand, mediate the relationship between Health Behaviors and renal diseases, diabetes, and death." (PMID 41290610, 2025). "Our results showed that FTY720 diminished TLOs formation in kidneys and decreased TLO-related chemokine CXCL13 and CCL19 expression, which is consistent with previous animal research on TLOs in EAE and diabetes." (PMID 33391465, 2021). "Of note, the requirement for TLS in T1D development is challenged by experiments showing that anti-CXCL13 treatment blocks organized TLS and GC formation in islets but fails to prevent diabetes in this model." (PMID 40909612, 2025). "In the autoimmune Non-Obese Diabetic (NOD) T1DM mouse model, CXCL13 and its cognate receptor, CXCR5, were highly expressed during the development of ELSs, especially in the early onset of diabetes." (PMID 35309354, 2022).
syphilis (12 papers, 2015 to 2025). A contagious bacterial infection caused by the spirochete Treponema pallidum. "CXCL13 is also thought to be implicated in infection with Treponema pallidum (the causative agent of syphilis), with CXCL13 levels within the CSF of syphilis patients being 100‐fold higher than those in uninfected individuals." (PMID 35702353, 2022). "However, more controlled studies are required to elucidate the change in CXCL13 after treatment in patients with syphilis at different stages." (PMID 33336020, 2020). "Third, in patients co-infected with HIV and syphilis, the presence of CXCL13, CXCL10 and CXCL8 in CSF could be associated with syphilis, HIV or both." (PMID 27650493, 2016). "In addition, whether CSF CXCL13 is more sensitive than leukocyte count is required to be validated in more patients with syphilis at different stages." (PMID 33336020, 2020). "However, patients with syphilis and HIV co-infection have been found to have higher CSF CXCL13 values than those with HIV infection only." (PMID 32331231, 2020). "In our study, elevated CSF and serum CXCL13 levels were observed in some secondary syphilis patients, but CSF TPPA was nonreactive, indicating that CXCL13 may be produced prior to the specific antibodies." (PMID 27650493, 2016).
experimental autoimmune encephalomyelitis (11 papers, 2015 to 2025). An autoimmune demyelinating disease of the central nervous system that is produced experimentally in animals by the injection of homogenized brain or spinal cord in Freund's adjuvant. "In line with our finding, the B cell infiltration after experimental autoimmune encephalomyelitis has been shown to be normal in the brain of CXCL13-deficient mice." (PMID 27894304, 2016). "Several studies in the animal model of MS, experimental autoimmune encephalomyelitis (EAE), have proposed an association between CXCL13 and MS." (PMID 32110891, 2020). "Likewise, using knockout animals, CXCL13 has been reported to be dispensable for the initial recruitment of B cells to CNS inflammation induced by either Sindbis virus infection or experimental autoimmune encephalomyelitis." (PMID 27207308, 2016). "In animal models of experimental autoimmune encephalomyelitis (EAE), the presence of CXCL13 has been associated with disease activity and the blockade of this chemokine could work as a potential complementary therapeutic strategy in patients with MS in order to postpone disease progression." (PMID 30345018, 2018). "CXCL13 is a ligand of CXCR5 and is found in B cell aggregates that develop in the inflamed meninges of mice with experimental autoimmune encephalomyelitis (EAE) and in humans with progressive multiple sclerosis (MS)." (PMID 31474986, 2019). "CXCR5+ T cells were detected in inflammatory infiltrates in spinal cords of mice with experimental autoimmune encephalomyelitis (EAE) and EAE was attenuated in CXCL13−/− mice." (PMID 28827539, 2017). "In experimental autoimmune encephalomyelitis (EAE), a MS murine model, blocking CXCL13 with an antibody or knocking it out entirely still allowed onset of disease to occur normally, but severity was attenuated over time, as shown by lower mean clinical scores and less activated microglia." (PMID 34868008, 2021). "In a murine model of experimental autoimmune encephalomyelitis, myelin-specific Tfh could not induce disease when transferred into recipient mice; however, anti-CXCL13 treatment (CXCL13: chemokine that binds to CXCR5, which is highly expressed on Tfh) attenuated Th17-mediated disease severity." (PMID 38835766, 2024).
colitis (10 papers, 2014 to 2025). Inflammation of the colon. "In colitis lesions, intense inflammation is associated with abundant TLSs, where CXCL13 and its receptor CXCR5, normally present in gut‐associated lymphoid tissue, also promote the formation of aberrant aggregates in ulcerative colitis." (PMID 40996881, 2025). "Compared with WT mice, Cxcl13-/- knockout mice had less symptoms of colitis, including longer survival, less weight loss, less disease activity, less colon length shorten, and less colorectal inflammatory infiltration." (PMID 36172372, 2022). "We next examined the effect of CXCL13 deficiency on pro-inflammatory cytokines secretion during DSS-mediated colitis." (PMID 36172372, 2022). "The regulatory B cells in the colon increased as colitis was alleviated in CXCL13-deficient mice." (PMID 38785804, 2024). "This could explain why CXCL13 deficiency can effectively alleviate DSS-induced colitis in mice." (PMID 36172372, 2022). "Experimental models further reveal that activation of the vagus nerve stimulates intestinal neurons to induce CXCL13 production in stromal cells, a mechanism that is lost following vagotomy, even though colitis itself continues to progress." (PMID 40996881, 2025). "We observed higher expression of Cxcr5 in mesenteric lymphatic B cells and higher expression of Cxcl13 in the intestine of colitis mice." (PMID 38785804, 2024). "We found that the mRNA expression of Cxcl13 was significantly increased in the colonic tissues of DSS-induced colitis rats." (PMID 38785804, 2024). "A higher level of serum CXCL13 was correlated with inflammatory responses in IBD patients (including UC and CD) and DSS-induced mice, and colitis was alleviated in CXCL13-deficient mice or those administrated anti-CXCL13 antibodies." (PMID 38785804, 2024). "RNA sequencing revealed increased Cxcr5 expression in MLB cells from colitis rats, while real-time PCR indicated an upregulation of its ligand Cxcl13 in the colon of colitis rats." (PMID 38785804, 2024). "Consistently, the Cxcl13-/- mice experienced less colon shortening, which was the characteristic of colitis." (PMID 36172372, 2022). "With C57BL/6 mice, we detected CXCL13 expression in the colorectal region of colitis and healthy mice using real-time PCR." (PMID 36172372, 2022). "Quantitative analysis also revealed significantly lower histological colitis scores in the colon of Cxcl13-/- mice." (PMID 36172372, 2022). "The deficiency of CXCL13 resulted in significantly decreased expression of inflammatory cytokines IL-21, IL-1β, IL-1α, IL-17, IL-6 and TNF-α in colon sites of mice with colitis." (PMID 36172372, 2022). "The deficiency of CXCL13 can effectively alleviate the occurrence and the development of DSS-induced colitis by limiting CD4+CXCR5+ T cells migration from mesenteric lymph nodes to secondary lymphoid organs, and thereby inducing local regulatory B cells increase in colon." (PMID 36172372, 2022). "Furthermore, Cxcl13-/- knockout mice were used to construct DSS-induced colitis model to verify the role of CXCL13 in IBD." (PMID 36172372, 2022). "In mice colitis model, we also found elevated levels of CXCL13 in colon tissue." (PMID 36172372, 2022). "However, little is known about the contribution of CXCL13 to the development of colon inflammation during inflammatory bowel disease." (PMID 36172372, 2022). "Consequently, NLRP12-deficient mice were highly susceptible to colitis and colitis-associated colorectal cancer through the increase in noncanonical NF-κB activation and expression of Cxcl13 and Cxcl12 as target genes that were associated with cancer." (PMID 34571825, 2021). "In conclusion, our study demonstrated a elevation of CXCL13 in both IBD patients and DSS-induced colitis mice, which contributed to the recruitment of CD4+CXCR5+ T cells to secondary lymphoid organs, thereby promoting the production of regulatory CD5+ B cells." (PMID 36172372, 2022).
colitis (continued). "In the current study, we investigate the role of CXCL13 in the development of both clinical patients with IBD and DSS-induced colitis mice model." (PMID 36172372, 2022). "In this study, we have demonstrated that the serum CXCL13 levels were markedly increased in both IBD patients and mice colitis models, and its expression level was positively correlated with the severity of inflammatory response." (PMID 36172372, 2022). "To ascertain whether CXCR5 plays a crucial role in MLB cells migration to the colon, we compared the mRNA expression of Cxcl13 (the specific ligand of Cxcr5) in colonic tissues of NC and DSS-induced colitis rats through real-time PCR." (PMID 38785804, 2024). "To investigate whether CXCL13 regulates the inflammatory response in IBD, we employed a classic DSS-induced experimental colitis model." (PMID 36172372, 2022). "Interestingly, DSS treatment resulted in a significant increase in the level of CXCL13 in colon tissue, suggesting increase expression of CXCL13 at site of intestinal inflammation along with DSS-induced colitis." (PMID 36172372, 2022). "Accordingly, we observed that the expression levels of genes encoding chemokines (Ccl3, Ccl4, and Ccl6), chemokine receptors (Ccr1, Ccr5, Cxcr2, Cxcl1, Cxcl2, and Cxcl13), and inflammatory factors (Mpo, Il-1β, and Il12) were increased in mice with DSS-induced colitis." (PMID 34795650, 2021). "Although the present study did not detect alterations in CXCL13 and CXCR5 expression in MLB cells from TNBS-induced colitis rats, we observed upregulated mRNA expression of Ccr8, a receptor for the T cell-derived chemokine Ccl1, in these rats." (PMID 40331987, 2025).
glioma (10 papers, 2020 to 2026). A benign or malignant brain and spinal cord tumor that arises from glial cells (astrocytes, oligodendrocytes, ependymal cells). "Collectively, our work reveals that FUOM induces M2-like macrophage polarization and promotes glioma progression by mediating CXCL13 secretion." (PMID 41957358, 2026). "The prognostic potential of CXCL13 gene in gliomas was verified by 529 LGGs and 166 GBMs in exon expression profiles and DNA methylation patterns." (PMID 35570844, 2022). "Decreased levels of DNA methylation occur in glioma patients with poor outcomes, which imply that demethylation acts as epigenetic modification to enhance CXCL13 expression." (PMID 35570844, 2022). "In this study, the prognostic potential of CXCL13 gene expression was demonstrated by 695 glioma samples from TCGA GBMLGG datasets." (PMID 35570844, 2022). "CXCL13 as an available prognostic biomarker for glioma outcome was illustrated by Kaplan-Meier curves (exon, p = 0.0002; methylation, p < 0.0001)." (PMID 35570844, 2022). "Direct comparison of BrM CD8+ TILs with glioma CD8+ TILs revealed CXCL13 as the most highly DEG." (PMID 37217652, 2023). "Consistent with the in silico analysis, the present immunohistochemistry result indicated a strong relationship between CXCL13 and poor prognosis of the glioma (p = 0.0039), supporting our initial hypothesis." (PMID 35570844, 2022). "Macrophage infiltration into the glioma TME was observed upon FUOM downregulation, with induced CXC motif chemokine ligand-13 (CXCL13) release in maintaining M2-like phenotype." (PMID 41957358, 2026). "In glioma grade IV, highly activated DEGs included STOM, IGHG4, CXCL13, MMP13, and CAPN6, while highly downregulated DEGs included JAZF1-AS1 and ELDR." (PMID 33948562, 2021).
metastatic disease (10 papers, 2008 to 2024). "One study showed that serum CXCL13 level was overexpressed in patients with metastatic disease compared with those of healthy controls." (PMID 37958571, 2023). "Nonetheless, elevated serum concentrations of CXCL13 could be detected in patients with metastatic disease, possibly reflecting differences between 2-D cultures and tumors." (PMID 31354634, 2019). "Finally, we detected significantly elevated serum concentrations of CXCL13 in patients with metastatic disease (n=54) as compared with controls (n=44) and disease-free patients (n=48)." (PMID 18781150, 2008). "Moreover, studies documented elevated CXCL13 serum levels in HCC patients, which correlate with tumor size, metastatic disease, advanced stages, and Alanine Transaminase/Aspartate Aminotransferase serum levels." (PMID 31354634, 2019). "Myofibroblast activation, immune infiltration, and induction of TGF-β and CXCL13 could be also observed upon castration of TRAMP mice, a model that develops metastatic tumors with neuroendocrine differentiation." (PMID 31354634, 2019). "Furthermore, given the elevated CXCL13 expression in the serum of patients with metastatic disease as compared with patients without evidence of tumour burden, this chemokine may also serve as a tumour marker." (PMID 18781150, 2008).